Y_RNA (Y RNA )
Gene: Miscellaneous RNA gene on chromosome 4 (143,309,466 to 143,309,566, forward strand). Ensembl gene ENSG00000200049.
Homologues: Orthologues: chimpanzee Y_RNA (99% identical), macaque Y_RNA (93% identical). Paralogues in human: Y_RNA (92% identical), Y_RNA (91% identical), RNY3P1 (90% identical), Y_RNA (90% identical), RNY3 (89% identical), Y_RNA (89% identical), Y_RNA (88% identical), Y_RNA (87% identical), Y_RNA (86% identical), RNY3P11 (85% identical), Y_RNA (85% identical), RNY3P14 (84% identical), and 97 more.